HIF1A (hypoxia inducible factor 1 subunit alpha)
Diseases named in the same sentence as HIF1A in open-access papers (continued):
Sharing a sentence is not in itself a finding about the gene and the disease.
Sepsis (continued). "Given its involvement in critical aspects of sepsis, HIF-1α has emerged as a potential therapeutic target for treating sepsis in humans." (PMID 38539163, 2024). "The review encompasses an analysis of the structural features, regulatory activation, and downstream signaling pathways of HIF-1α, alongside its mechanism of action in the pathophysiological processes of sepsis." (PMID 38539163, 2024). "Conversely, Norisoboldine and the flavonoid compound Cynaroside can mitigate sepsis-induced acute lung injury by promoting the polarization of macrophages from M1 to M2 via the PKM2/HIF-1α pathway." (PMID 39712019, 2024). "In sepsis‐induced myocardial dysfunction, phlorizin, a new caloric restriction mimetic, activates autophagy and protects cardiomyocytes through the HIF‐1α/BNIP3 axis." (PMID 39611400, 2024). "Further research affirms that throughout the progression of sepsis-induced acute lung injury, HIF-1α can intensify glucose metabolism in tracheal epithelial cells, induce apoptosis of type II alveolar (AT-II) cells, and expedite the development of ARDS." (PMID 39712019, 2024). "Under hypoxic conditions in sepsis, HIF-1α acts as a key upstream molecule in glycolysis, promoting the expression of key glycolytic enzymes such as GLUT1, HK2, and PFKFB3." (PMID 39712019, 2024). "During sepsis, the activation of HIF-1α governs the host’s adaptive response to hypoxia and influences the release of inflammatory mediators, as well as the balance between anti-inflammatory and immune tolerance states." (PMID 38539163, 2024). "Future studies can explore the molecular mechanisms and pathways of HIF-1α in sepsis, with the potential to reveal new targets and strategies for the early diagnosis and treatment of sepsis." (PMID 38539163, 2024). "Hypoxia acts as the link connecting the pathophysiological changes in sepsis to the molecular alterations of hypoxia-inducible factor-1α (HIF-1α)." (PMID 38539163, 2024). "For instance, rabeprazole acts as a potent HIF-1α inducer, facilitating vascular repair and reducing sepsis-induced lung inflammation through the endothelial HIF-1α/FoxM1 signaling pathway." (PMID 38539163, 2024). "A research team previously found that the HIF-1α activator yielded a protective effect against sepsis-induced intestinal mucosal damage." (PMID 39525113, 2024). "Further, AV attenuates the increased levels of TGF-β1, IL-6, and HIF-1α in the mouse models of pulmonary fibrosis, and sepsis." (PMID 38049897, 2023). "The role of HIF-1α in inflammation has been studied in animal models of sepsis, rheumatoid arthritis, and chronic cutaneous inflammation, using conditional gene targeting techniques that allow tissue-specific deletion of HIF-1α or VHL genes." (PMID 36611440, 2023). "We also explored the TASE effects in HIF-1α, described as the key transcription factor leading to endotoxin tolerance in sepsis monocytes through IRAK-M expression." (PMID 37047205, 2023). "For example, LDHA downregulation mediated by the PI3K/Akt-HIF-1α pathway results in glycolytic inhibition, which leads to neutrophil immunosuppression during sepsis." (PMID 37728418, 2023). "Functional plasticity or reprogramming occurs in circulating monocytes during sepsis, and the expression and activity of HIF-1α are upregulated, which is consistent with our results." (PMID 36937929, 2023). "Innate immune cells lack myeloid-specific HIF-1α, resulting in an inability to produce β-glucan-induced protection against Staphylococcus aureus-induced sepsis." (PMID 37434129, 2023). "This led to the identification of two iron metabolism genes related to sepsis prognosis (HIF1A and SLC25A37)." (PMID 36937929, 2023). "In sepsis, SCAMP5 shows promise for diagnosis biomarker, and the PI3K/Akt-HIF-1α pathway modulates immunological glycolysis, thereby controlling neutrophil function in sepsis patients." (PMID 38332910, 2023).
Sepsis (continued). "A previous study found that HIF-1α promoted the production of inflammatory cytokines from macrophages, including IL-6, IL-12p70, and IL-1 in LPS-induced sepsis." (PMID 37709757, 2023). "The HIF-1α pathway is one of the key mechanisms involved in the monocyte phenotype during sepsis; thus, we explored the effect of TASE on this pathway." (PMID 37047205, 2023). "In sepsis, HIF-1α has been described as a key component in numerous phases of inflammatory responses." (PMID 37367740, 2023). "We conclude that HIF1α and HIF2α are activated in hepatocytes in sepsis, but their contribution to the mechanisms leading to lethality are minimal." (PMID 37006237, 2023). "HIF1α also has a vital role in the initial metabolic shift from oxidative phosphorylation to glycolysis during sepsis, and attenuates the pro-inflammatory response by inducing IRAKM production, a negative regulator of TLR signaling." (PMID 37006237, 2023). "Taken together, these studies suggest an important role for HIF1α during various stages of sepsis, despite most animal experiments applied suboptimal sepsis model systems, like the LPS-induced endotoxemia mouse model." (PMID 37006237, 2023). "Rabeprazole improves vascular repair and the resolution of sepsis-induced inflammatory lung injury through the endothelial HIF-1α/FoxM1 signaling axis." (PMID 35563731, 2022). "The previous study by Fitzpatrick and his team demonstrated that HIF-1α played an important time-dependent role during sepsis; regulating the inflammatory response during the acute stage and the regulating protective response during the later stages." (PMID 35576220, 2022). "Compared with the sepsis group, the sepsis + DMOG group exhibited significantly higher expression levels of HIF-1α and ZO-1, occludin and Claudin-1 in the intestinal mucosa (P < 0.05) (P < 0.05)." (PMID 35576220, 2022). "Through a series of assays, we testified the mechanism of sepsis-induced myocardial injury from miR-124-3p/SP1/HDAC4/HIF-1α axis." (PMID 35091534, 2022). "Other studies also demonstrate an important role of HIF-1α in vascular repair in animal models other than sepsis." (PMID 35563731, 2022). "Genes encoding the proteins involved in glycolysis and the hypoxia-inducible factor (HIF)-1α pathway were significantly upregulated in the PMNs from patients with sepsis relative to those of healthy volunteers." (PMID 35090526, 2022). "Transcriptomics showed significant changes in glycolysis and the mTOR/HIF-1α signaling pathway during sepsis." (PMID 35090526, 2022). "Downregulation of HIF-1α in neonatal macrophages has been indicated to relate with the attenuation of sepsis-induced lung injury." (PMID 35091534, 2022). "T3 treatment in experimental sepsis prevented cardiac and liver tissue hypoxia (pO2 less than 10 mmHg, a threshold below which HIF-1α-regulated mechanisms are activated)." (PMID 35805716, 2022). "FDA-approved drugs that stimulate HIF-1α/FoxM1 signaling, such as Rabeprazole, represent promising candidate therapies for patients with severe sepsis and ARDS." (PMID 35563731, 2022). "Studies have shown that exosomes released from bone marrow mesenchymal stem cells (BMSCs) can reduce macrophage glycolysis by inhibiting HIF-1α, thereby attenuating sepsis-inducing lung injury." (PMID 35847986, 2022). "In conclusion, Rabeprazole is a potent inducer of HIF-1α that promotes vascular repair and the resolution of sepsis-induced inflammatory lung injury via endothelial HIF-1α/FoxM1 signaling." (PMID 35563731, 2022). "sepsis induces cognitive deficits, and mice with cognitive deficits improve after administering the HIF-1α inhibitor echinomycin." (PMID 36569834, 2022). "In another study of HIF-1α signaling during post-sepsis vascular repair in mouse lungs, promoter analysis identified Sox17 as a transcriptional target of HIF-1α." (PMID 35053299, 2022).
Sepsis (continued). "Tissue hypoxia during sepsis triggers HIF-1α activation for adaption to hypoxia, but overexpression of HIF-1α, in turn, leads to mitochondrial dysfunction." (PMID 35163007, 2022). "In this study, HIF-1α has a protective effect on sepsis induced intestinal mucosa 24 hours after CLP." (PMID 35576220, 2022). "We hypnoses that HIF-1α will present its protection effect on sepsis-induced intestinal mucosa injury through modulation of inflammatory and oxidative process." (PMID 35576220, 2022). "Other evidences suggested that elevated HIF-1α levels in the early stages of sepsis/septic shock are detrimental to survival." (PMID 35576220, 2022). "The role of hypoxia-inducible factor-1α (HIF-1α) in the intestinal barrier disfunction related to sepsis remained unclear." (PMID 35576220, 2022). "Hypoxia-inducible factor 1α (HIF-1α), a key transcriptional factor in the regulation of hypoxic response, plays a critical role in the development of immune re-programming in sepsis." (PMID 36016936, 2022). "Other studies showed that HIF-1α plays a crucial role in the development of myeloid cell-mediated inflammation during LPS-induced sepsis." (PMID 35090526, 2022). "Our previously published study shows that FoxM1 is the downstream target of HIF-1α that is responsible for vascular repair following sepsis challenge." (PMID 35563731, 2022). "In another study of HIF-1α signaling during post-sepsis vascular repair in mouse lungs, promoter analysis identified Sox17 as a reparative transcriptional target of HIF-1α." (PMID 35563731, 2022). "In this case, we targeted to explore in detail the relative mechanism of microRNA (miR)-124-3p in sepsis-induced myocardial injury via the specific protein 1/histone deacetylase 4/hypoxia-inducing factor 1α (SP1/HDAC4/HIF-1α) axis." (PMID 35091534, 2022). "The interaction between ROS and HIF-1α has implications for both cancer (HIF-1α upregulation often confers a survival advantage to cancerous cells) and sepsis." (PMID 35928940, 2022). "C57BL/6J male mice were divided into four groups, using a random number table method: control group, sham group, sepsis group, sepsis+HIF-1α activity inhibitor (echinomycin) group." (PMID 36569834, 2022). "Future studies are required to investigate the role of HIF-1α in neutrophils’ immune function in the early stage of sepsis." (PMID 35090526, 2022). "The regulatory role of HIF-1a in different organs on different stages of sepsis needs to be further clarified." (PMID 35576220, 2022). "Compared with that in the sham group, the expression level of HIF-1α was significantly increased in the sepsis group (P < 0.05), and the expression levels of ZO-1, occludin and claudin-1 were significantly decreased (P < 0.05)." (PMID 35576220, 2022). "The purpose of the present study is to investigate the role of HIF-1α on oxidative damage, the intestinal mucosal permeability, structural and morphological changes during sepsis." (PMID 35576220, 2022). "This response is common after sepsis, myocardial infarction and trauma and involves HIF-1α-dependent and-independent regulated mechanisms." (PMID 35805716, 2022). "In a word, miR-124-3p targeted SP1 to regulate HDAC4 and HIF-1α, thereby attenuating the pathology of sepsis-induced myocardial injury." (PMID 35091534, 2022). "We previously showed that vascular repair and the resolution of sepsis-induced inflammatory lung injury is dependent upon endothelial HIF-1α/FoxM1 signaling." (PMID 35563731, 2022). "In this study, we found that the expression of HIF-1α in the hippocampus of sepsis mice increased, the hippocampus structure was damaged, hippocampus neurons were apoptosis, and the mice developed cognitive dysfunction." (PMID 36569834, 2022). "The aim of this study was to identify a candidate inducer of HIF-1α/FoxM1 signaling for the treatment of sepsis and ARDS." (PMID 35563731, 2022). "In sepsis-induced lung injury, silencing HIF-1α also presents its anti-inflammatory and anti-oxidant effects." (PMID 35091534, 2022).
Sepsis (continued). "The purpose of this study was to investigate the effect of HIF-1α on intestinal mucosal barrier injury in sepsis." (PMID 35576220, 2022). "During sepsis, LPS-induced HIF-1α expression upregulates the production of ROS, inflammatory cytokines, and proapoptotic proteins (e.g., caspase-3, BNIP-3, and Beclin-1), contributing to inflammation and apoptosis." (PMID 33567713, 2021). "During sepsis, LPS-induced HIF-1α activation promotes the production of inflammatory cytokines (including TNF-α, IL-1β, and IL-6) and proapoptotic mediators, resulting in inflammation and apoptosis." (PMID 33567713, 2021). "Conversely, HIF-1α mRNA levels in blood and protein expression in leukocytes were decreased in patients with severe sepsis." (PMID 34447792, 2021). "Altogether, this evidence suggests that increased HIF-1α levels in the early phase of sepsis/septic shock is detrimental for survival." (PMID 34447792, 2021). "Both Gln and Leu suppressed monocyte infiltration into muscles, attenuated inflammatory mediator production, inhibited calpain activity, and downregulated HIF-1α mRNA expression in the early and/or late phases of sepsis." (PMID 34884807, 2021). "Tissue oxygen below 10 mmHg results in activation of HIF1α-dependent regulatory mechanisms that promote pathologic angiogenesis, changes in immune response, and determine sepsis-induced injury progression." (PMID 34945151, 2021). "HIF-1α also triggers in sepsis a metabolic switch towards glycolysis (fetal phenotype) with important physiological consequences and additional promotion of M1- (proinflammatory) macrophage activity and response." (PMID 34945151, 2021). "For instance, HIF-1α activation has been implicated in the proinflammatory response of myeloid cells during sepsis, and deletion of HIF-1α in myeloid cells afforded protection against LPS-induced mortality." (PMID 34288817, 2021). "There is a combination of systemic inflammation, hypoxemia, and eventual tissue hypoxia in sepsis, inducing signals for HIF-1α accumulation." (PMID 34062710, 2021). "XJDHT can improve sepsis by suppressing aerobic glycolysis through downregulation of the TLR4/HIF-1α/PKM2 signalling pathway." (PMID 34759927, 2021). "The preventive effects of exosomes from bone marrow MSC against sepsis, including mitigating acute lung injury and inhibiting HIF-1α in mice with endotoxemia, have also been reported." (PMID 35056093, 2021). "Taken together, hypoxia-induced HIF-1α activation is an additional “second key-trigger” for tissue remodeling after sepsis." (PMID 34945151, 2021). "Conversely, the amount of IL-10 was lower in the adenovirus Ade-HIF-1α group compared with the sepsis model group and the Ade-control group." (PMID 32089644, 2020). "Levels of GILZ (p = 0.018), ZFP36 (p = 0.006), FKBP5 (p = 0.012) and NRF2 (p = 0.009) mRNA were reduced, whereas CSE (p = 0.012) and HIF1α (p = 0.020) were elevated in sepsis." (PMID 32477273, 2020). "Taken together, monocytes undergo reprogramming to generate immunosuppression through the HIF-1α signaling pathway in the late phase of sepsis." (PMID 32089644, 2020). "Whereas it has been reported that HIF-1α expression was significantly suppressed in sepsis, several data convincingly showed that circulating EPCs levels in septic patients are elevated." (PMID 32593288, 2020). "Compared to the control group (Isoflurane or Propofol + no sepsis), in rats anesthetized with isoflurane +sepsis led to a significant increase in the hepatic protein expression of HIF-1α (51%) as well as in Propofol +sepsis group (47%)." (PMID 33392215, 2020). "During sepsis, HIF-1α, stimulated by LPS, activates the generation of inflammatory cytokines (including TNF-α, IL-1β and IL-6) and proapoptotic proteins, leading to inflammation and apoptosis." (PMID 32353952, 2020).
Sepsis (continued). "In a clinical study, the levels of IL-1β, IL-6, TNF-α, etc., except for IL-10, were inhibited in the late phase of sepsis, while, in an animal study, the immune suppression status was attenuated with administration of the adenovirus Ade-HIF-1α." (PMID 32089644, 2020). "Deletion of endothelial cell HIF-1A expression inhibited endothelial proliferation and attenuated vascular repair processes in a model of sepsis-induced lung injury." (PMID 33537342, 2020). "Monocytes undergo immunosuppression in the late phase of sepsis through the HIF-1α signaling pathway, which thus inhibited the production of proinflammatory cytokines and induced the upregulation of protein PD-L1 expressed on the monocytes." (PMID 32089644, 2020). "Taken together, based on our study, the immune checkpoint protein PD-L1 overexpressed in monocytes during the late phase of sepsis contributed to immunosuppression in severe pneumonia-induced sepsis through the HIF-1α signaling pathway." (PMID 32089644, 2020). "VEGF, a well-known HIF-1α target gene, has been demonstrated to be a critical mediator of sepsis-related morbidity and mortality." (PMID 32353952, 2020). "Bmal1 loss-of-function in M1-activated macrophages causes mitochondrial dysfunction, thereby potentiating mROS production and Hif-1α protein stabilization, which probably contributes to the increased sepsis-induced inflammatory damage reported for M-BKO mice." (PMID 32396064, 2020). "In macrophages, on the other hand, HIF-1α promotes a proinflammatory phenotype during LPS-induced sepsis, whereas HIF-2α drives the development and function of immunosuppressive TAMs that inhibit T-cell activity." (PMID 29953680, 2019). "Suppressed HIF-1α induced iNOS/NO and cytokine production was found in the peritoneal macrophages, suggesting an important role of myeloid HIF-1α in sepsis survival." (PMID 31555665, 2019). "Downstream signaling of the TLR's leads to the activation of a wide range of transcription factors which promote the stabilization of HIF-1α during sepsis, including; mitogen-activated protein kinase (MAPK), MAPK phosphatases-1 and NFκB." (PMID 31555665, 2019). "A role for HIF-1α in the lung was also shown in a septic lymph model of sepsis, also showing that HIF-1α is activated in a pseudo-hypoxic manner." (PMID 31380363, 2019). "The hyperinflammatory phase of sepsis is accompanied by a metabolic switch from oxidative phosphorylation to HIF-1α mediated glycolysis." (PMID 31555665, 2019). "Pharmacological activation of AMPK in macrophages results in diminished LPS-induced HIF-1α accumulation, which in turn diminishes the severity of lung injury following polymicrobial sepsis." (PMID 31555665, 2019). "Activation of HIF-1α by TLR's is essential in the metabolic reprogramming of innate immune cells during sepsis." (PMID 31555665, 2019). "In contrast, 5,7-dihydroxy-8-methoxyflavone protected against sepsis-induced acute lung injury in part due to inhibition of HIF-1α accumulation." (PMID 31555665, 2019). "During sepsis, cells are in a state of hypoxia and potentially show high expression levels of HIF-1α protein." (PMID 31781604, 2019). "Previous studies have shown that the molecular mechanism underlying the switch from OXPHOS to glycolysis during innate immune cell response to sepsis requires HIF-1α." (PMID 31555665, 2019). "HIF-1α activated by LPS contributed to cytokine activation, symptomatology, and lethality in a LPS-induced sepsis in vivo model." (PMID 31480519, 2019). "Overall, the current study found that inhibition of miR-31 protects against intestinal barrier dysfunction through suppression of the NF-κB/HIF-1α pathway by targeting HMOX1 in rats with sepsis." (PMID 30340459, 2018). "Herein, we evaluate the effect of microRNA-31 (miR-31) on intestinal barrier dysfunction through NF-κB/HIF-1α pathway by targeting HMOX1 in rats with sepsis." (PMID 30340459, 2018).